STAT3 (signal transducer and activator of transcription 3)
Diseases named in the same sentence as STAT3 in open-access papers (continued):
Sharing a sentence is not in itself a finding about the gene and the disease.
breast cancer (continued). "PTPMeg2 is an important phosphatase for the dephosphorylation of STAT3 and plays a critical role in breast cancer development." (PMID 22394684, 2012). "Tyr23 phosphorylation of Anxa2 promotes the proliferation and invasion of human breast cancer SK-BR-3 cells and the phosphorylation of Stat3 in the nucleus." (PMID 23691485, 2012). "Levels of PTPMeg2 and phosphorylated STAT3 were inversely correlated in breast cancer tissues (P = 0.004)." (PMID 22394684, 2012). "Pan-Rac inhibition of proliferation precedes down-regulation of STAT3 activity, defining it as the last step in Rac activation during human breast cancer invasion." (PMID 22689141, 2012). "Ealrier reports also mentioned that downregulation of STAT3 induced apoptosis in human glioma and breast cancer cells." (PMID 22984561, 2012). "Stat3 was identified as a critical node in self-renewal based on an ongoing lentiviral shRNA screen being conducted in two breast cancer cell lines SUM159 and BT549." (PMID 22879872, 2012). "Our previous studies of PR function demonstrated that Stat3 is a key mediator of progestin effects in breast cancer." (PMID 22583478, 2012). "Signal transducer and activator of transcription 3 (STAT3) is important for breast involution after weaning and a prognostic factor for breast cancer." (PMID 22485142, 2012). "Other critical factors such as p-STAT5, p-STAT3, p-IGF-1R, Jak2 and Brk causing breast cancer were also suppressed by HSE." (PMID 22792362, 2012). "Even in breast cancer cell lines, including MCF-7 and MDA-MB-231, STAT3 was previously shown to be associated with cell proliferation." (PMID 23554768, 2012). "Our previous findings demonstrated that HRG induces a strong Stat3 activation in breast cancer cells and, notably, that this effect is mediated via HRG co-option of PR function as a signaling molecule." (PMID 22583478, 2012). "This compound has also been shown to reduce the phosphorylation levels of Src, JAK1, and STAT-3 in MDA-MB-468 human breast cancer cells." (PMID 22554053, 2012). "The analysis also revealed that the increased STAT3 level was correlated with reduced PTPMeg2 expression in the breast carcinoma (correlation coefficient is -2.65, p = 0.023)." (PMID 22394684, 2012). "Samples from breast carcinoma (n = 73) were subjected to a pair-wise Pearson correlation analysis for the correlation of levels of PTPMeg2 and phosphorylated STAT3." (PMID 22394684, 2012). "In vitro killing competence of MSCs carrying Adv-Stat3(-) toward breast cancer and melanoma was performed using co-culture system of transwell plates." (PMID 22054049, 2011). "Stat3 is persistently tyrosine phosphorylated in a large number of tumors of epithelial origin including breast cancer." (PMID 22140473, 2011). "Activated Stat3 is a direct transcriptional regulator of Twist in breast cancer which is a critical regulator of metastatic progression." (PMID 22140473, 2011). "One explanation for this observation is that cytokines such as IL-6 which mediate Stat3 activation in breast cancers are expressed at higher levels in lymphatic tissue resulting in increased pStat3." (PMID 22140473, 2011). "Activation of the Stat3 pathway in breast cancer can occur through many pathways, including those of EGFR, HER2, IL-6 receptors, IL-11 receptors, and progesterone receptors." (PMID 21689417, 2011). "Constitutive activation of Stat3 occurs commonly in cancer, including breast cancer and has been demonstrated to contribute to tumorigenic processes." (PMID 21689417, 2011). "Inhibition of Stat3 activation in breast cancer cells inhibits growth and neo-angiogenesis, and potentiates a response to the chemotherapeutic agent doxorubicin." (PMID 22140473, 2011). "Further analysis of Necdin expression demonstrated repression in a STAT3-dependent manner in human melanoma, prostate and breast cancer cell lines." (PMID 22046235, 2011).
breast cancer (continued). "In the present study, we investigated the ability of MSCs to deliver an E1A mutant CRAd targeting Stat3 to orthotopic breast cancer." (PMID 22054049, 2011). "Differentially expressed genes included several previously identified Stat3 targets such as Twist, Snail and IL-8, and this suggested our analysis at least partially captured a molecular profile of Stat3 transcriptional activation in breast cancer." (PMID 22140473, 2011). "Since EGFR and Src signaling pathways contribute to STAT3 activation in breast cancers, we evaluated Necdin expression levels in human breast cancer cell lines with different levels of endogenous STAT3 activity." (PMID 22046235, 2011). "siRNA-mediated Src knock-down alone, and simultaneous knock-down of Src and Stat3 and/or cMyc inhibited the neoplastic phenotype of a highly metastatic human model breast cancer cell line, MDA-MB-435S." (PMID 21541295, 2011). "We have shown that Stat3 regulates expression of MMP-9 in breast cancer and integrin ß6 in prostate cancer which are critical regulators of invasion and migration." (PMID 22140473, 2011). "Autocrine IL-6 production, a principal mediator of Stat3 activation in breast tumors, was found to be elevated in human mammary cancer/stem cells." (PMID 22140473, 2011). "We also demonstrated that Necdin expression is repressed in several tumor cell types, including melanoma, prostate and breast cancer cell lines, and is inversely correlated with STAT3 activity." (PMID 22046235, 2011). "Jab1 promoter analysis led to the identification of C/EBP-β, GATA-1, and Stat3 as positive regulators of Jab1 transcription in breast cancer cells." (PMID 21689417, 2011). "Taken together, it is evident that both IL-6 and Src signaling through Stat3 is contributing to Jab1 transcription and increased expression in breast cancer." (PMID 21689417, 2011). "EMSA and ChIP assays confirmed that C/EBP, GATA1 and Stat3 bind to Jab1 promoter in breast carcinoma cells." (PMID 21689417, 2011). "siRNA knockdown of Src reduced the Jab1-promoter activity, similar to the results seen when Stat3 was inhibited in breast carcinoma cells." (PMID 21689417, 2011). "Stat3 knockdown in murine models of ErbB2-mediated breast carcinoma altered epithelial adhesion and polarity." (PMID 22140473, 2011). "IL-6/Stat3 signaling has been shown to inhibit E-Cadherin expression in models of prostate and breast cancer." (PMID 20929542, 2010). "Our previous study demonstrated that heregulin-β-induced MMP-7 expression was regulated by HER2-mediated STAT3 and AP-1 activation in human breast cancer cell lines." (PMID 20939893, 2010). "In various types of malignant tumours, including leukaemia and cancers of the breast, head and neck, melanoma, prostate, pancreas, and colon, activation of STAT3 is aberrantly increased." (PMID 20461084, 2010). "When constitutively activated, STAT3 plays an important role in tumorigenesis, as shown in human breast cancer." (PMID 20565793, 2010). "Our result is consistent with recent reports showing that the novel Stat3 inhibitor, Indirubin, significantly induces apoptosis in human breast cancer cells." (PMID 20459702, 2010). "Recent report has shown that CDDO-Me inhibits activation of the JAK/Stat3 pathway by forming adducts with both JAK1 and Stat3 in human cervical and breast cancer cells." (PMID 20459702, 2010). "Earlier findings have shown that STA-21, a polyphenol, can inhibit STAT3 activities and induce cell death in breast cancer cells." (PMID 19127268, 2009). "Stat-3 is a well-defined c-Src target, in invasive breast cancer cells and animal models, and is required for experimental breast cancer metastasis; in addition, its activity correlates with that of c-Src in advanced breast cancer." (PMID 19583841, 2009). "It is well-known that STAT3 and to some extent STAT1 is activated in breast cancers and that constitutively active mutants of STAT3 promote the growth and survival of tumor cells thereby contributing to malignancy." (PMID 19338666, 2009).
breast cancer (continued). "It is well-known that STAT3 and to some extent STAT1 is activated in breast cancers and that constitutively active mutants of STAT3 promotes the growth and survival of tumor cells thereby contributing to malignancy." (PMID 19338666, 2009). "S3I-201 inhibited Stat3 homodimerization, DNA binding, induction of cyclin D1, Bcl-xL and survivin and induced apoptosis of v-Src-transformed NIH3T3 cells and breast cancer cell lines with constitutively active Stat3 in the 30 to 100 μM range." (PMID 19274102, 2009). "All 5 selective compounds inhibited nuclear-to-cytoplasmic translocation of Stat3, while 3 of 5 compounds induced apoptosis preferentially of breast cancer cell lines with constitutive Stat3 activation." (PMID 19274102, 2009). "The type II receptor complex activates OSM-specific signaling pathways via the JNK/SAPK and Stat1/Stat5 pathways, whereas both type I and type II complexes activate Stat3 and Erk as common signaling pathways in breast cancer cells." (PMID 19662090, 2009). "Summary of activity of compounds that are selective for Stat3 in inducing apoptosis of breast cancer cell lines." (PMID 19274102, 2009). "Two compounds—Cpd3 and Cpd30—induced apoptosis of the three breast cancer cell lines with constitutive Stat3 activity—MDA-MB-468, MDA-MB-231 and MDA-MB-435 —with EC50 values ranging from 2.3 to 26.9 μM and from 6.4 to 92.2 μM, respectively." (PMID 19274102, 2009). "STA-21 treatment of cells disrupted Stat3/DNA complexes, abrogated Stat3 translocation into the nucleus, inhibited expression of proteins such as Bcl-XL and Cyclin D1 and induced the apoptosis of breast cancer cell lines." (PMID 19274102, 2009). "The results shown here demonstrate that in well-differentiated mouse mammary tumors the constitutive activation of Stat3 would be mostly dependent on overexpression of LIF." (PMID 17925034, 2007). "This suggested that autocrine/paracrine LIF would be responsible for Stat3 activation in mouse mammary tumors." (PMID 17925034, 2007). "High levels of LIF expression and activated Stat3 were found in mammary tumors growing in vivo and in their primary cultures." (PMID 17925034, 2007). "To address this issue, in the present study we evaluated LIF expression and its ability to induce Stat3 tyrosine phosphorylation in mouse mammary tumors." (PMID 17925034, 2007). "To examine the potential mechanisms involved in mediating Stat3 phosphorylation, we examined breast cancer-derived cell lines expressing high levels of pStat3." (PMID 17531096, 2007). "Our results in mouse mammary tumors also show an association between LIF-R expression and Stat3 activation with a less aggressive phenotype." (PMID 17925034, 2007). "Clinical studies demonstrated that elevated levels of tyrosine-phosphorylated Stat3 (pStat3) in patients with stage II breast cancer correlated with an incomplete response to neo-adjuvant chemotherapy (a poor prognostic feature)." (PMID 17531096, 2007). "Since STAT3 is normally a transiently activated pro-apoptotic factor in mammary epithelial cells undergoing forced involution, the constitutive activation of STAT3 in breast cancers and its role as an oncogene is an apparent paradox." (PMID 17295906, 2007). "The induction of apoptosis by blocking Stat3 pathway in sarcoma cells expressing elevated levels of p-Stat3 is further supported using STA-21 that is an effective Stat3 inhibitor in breast cancer and some other cancer cells [and unpublished data]." (PMID 17598902, 2007). "The data presented here suggest that the principal mediator of Stat3 activation in breast cancer is through the IL-6 family of cytokines activating the gp130/Jak signaling pathway." (PMID 17531096, 2007). "A number of different tyrosine kinases, including the epidermal growth factor receptor (EGFR) family of tyrosine kinases, Src, and Jaks, have been described as mediating Stat3 phosphorylation in both primary tumors and breast cancer-derived cell lines." (PMID 17531096, 2007).
breast cancer (continued). "We examined six breast cancer-derived cell lines expressing high or low levels of tyrosine-phosphorylated Stat3 (pStat3) as well as primary breast cancer specimens." (PMID 17531096, 2007). "Both STAT5b and STAT3 are activated by several kinases overexpressed in breast cancer, including the EGFR, HER2, and c-Src." (PMID 17997837, 2007). "In well-differentiated mammary cancer cells, constitutive activation of Stat3 would therefore depend on LIF and LIF-R expression, as occurs in normal mammary epithelium." (PMID 17925034, 2007). "In summary, a principal mechanism of Stat3 activation in breast cancer is through the IL-6/gp130/Jak pathway." (PMID 17531096, 2007). "The results presented here show that LIF is overexpressed in MMTV-induced mammary carcinomas, in which, as a paracrine/autocrine factor, it is the main one responsible for Stat3 activation." (PMID 17925034, 2007). "Signal transducer and activator of transcription 3 (Stat3) is constitutively tyrosine-phosphorylated in approximately 50% of primary breast carcinomas." (PMID 17531096, 2007). "We have also characterized a Src/Stat3 responsive region on the HGF promoter identifying a Stat3 consensus binding site at nt-95 that has been demonstrated to be required for HGF promoter activation by Src/Stat3 in mouse mammary carcinoma cells." (PMID 17967179, 2007). "Numerous studies suggested constitutively activated Stat3 plays an oncogenic role in many types in human cancers including breast cancer." (PMID 16288304, 2005). "Supershift analysis suggests that Stat1 and possibly other members of the STAT family of signalling factors, including Stat3, are activated in breast cancer tissues." (PMID 7710952, 1995). "Moreover, KAT2A expression was significantly correlated with a STAT3 activity signature based on the GSVA analysis across metastatic breast cancer patients." (PMID 41826695, 2026). "In breast cancer, STAT3 activation via EGFR signaling promotes SOX2 expression." (PMID 41511366, 2026). "Therefore, we concluded that this provides evidence for the palmitoylation-induced KAT2A activity via STAT3 in breast cancer patients with lung metastases." (PMID 41826695, 2026). "Indeed, we found that signatures indicative of DDR1 and STAT3 signaling were increased in lung compared to brain metastases of breast cancer patients." (PMID 41826695, 2026). "In addition, TAMs secrete high levels of IL-6 increasing stemness markers (i.e. SOX2, OCT3/4 and NANOG) and consequently CSCs expansion in breast cancer cells via STAT3 pathway supporting tumor cells migration and angiogenesis." (PMID 39981232, 2025). "Dysregulation of STAT3 signaling can lead to a variety of diseases, including breast cancer." (PMID 40507264, 2025). "Moreover, dual targeting of redox APE1 and STAT3 signaling reduces cell viability, proliferation, migration, invasion potential and induces cell death by apoptosis in breast cancer cells." (PMID 41090323, 2025). "Although this loop was identified in breast cancer, similar mechanisms may operate in digestive tumors given STAT3’s established oncogenic role in PC." (PMID 40746536, 2025). "Furthermore, IL − 6/JAK/STAT3 signaling was significantly enriched among the predicted driver genes in basal-like breast cancer." (PMID 40258059, 2025). "Although both APE1 and STAT3 are important proteins in tumor progression, the crosstalk between these proteins is still unknown in breast cancer and processes related to tumor aggressiveness." (PMID 41090323, 2025). "Special attention was given to STAT3 to evaluate its potential value in breast cancer." (PMID 40076902, 2025). "For example, MEST induces Twist-1-mediated EMT via STAT3 activation in breast cancers." (PMID 40830747, 2025). "However, the combined signaling of these proteins has not been described before, which suggests the co‐participation of APE1 and STAT3 in regulating the aggressiveness in breast cancer." (PMID 41090323, 2025).
breast cancer (continued). "Gene expression analysis showed that GPNMB+ cells significantly upregulated genes involved in invasion and/or tissue remodeling, including EGFR, a direct interactor of GPNMB in breast cancer cells, its downstream targets (STAT3, MMP 2-3-9) and ITGB4, TGFβ, VEGF and VCAM." (PMID 40528051, 2025). "Additionally, upregulation of the IL-6/STAT3 pathway has been detected in ER + breast cancer resistant to CDK4/6i palbociclib, which mediates the upregulation of EMT and BCSCs pathways." (PMID 40949156, 2025). "However, rescue experiments were not conducted in vivo and at the cellular level to further prove that POC1A can better support POC1A to regulate the proliferation, migration and invasion of breast cancer by affecting STAT3 phosphorylation directly." (PMID 40830747, 2025). "Additionally, another study indicated that methyl selenite significantly inhibits breast cancer growth by suppressing the JAK2/STAT3 signaling pathway." (PMID 40821907, 2025). "Furthermore, the overexpression of HER2 triggers the HER2-IL-6- signal transducer and activator of transcription 3 (STAT3) signaling cascade, which stimulates breast cancer stem cells to self-renew and develop resistance to anti-HER2 therapy." (PMID 40584290, 2025). "Interestingly, STAT3 is activated by moderate levels of ROS, and mitochondrial STAT3 phosphorylation enhances murine 4T1 breast cancer cell development by increasing the complex I conjugated system and decreasing ROS levels." (PMID 40028033, 2025). "Notably, in breast cancer tissues, the number of STAT3+ cells within the tumor regions were sig-nificantly greater than that observed in the stromal regions (p < 0.0001)." (PMID 40636126, 2025). "Therefore, the main objective is the study of crucial roles of exosomes in breast cancer behaviour, drug resistance, and progression via STAT3 signaling pathways in TNBC." (PMID 40952540, 2025). "Additionally, the anti-apoptotic signals stimulated by STAT3 contribute to the limited response of breast cancer cells to HDAC inhibitors and the HER2 inhibitor lapatinib." (PMID 40949156, 2025). "Moreover, FTO promotes the doxorubicin resistance driven by signal transducer and activator of transcription 3 (STAT3) in breast cancer." (PMID 40483535, 2025). "Notably, MTH1 has previously been shown to regulate the PI3K/AKT pathway in gastric cancer and the STAT3 pathway in breast cancer." (PMID 40806307, 2025). "In neuroblastoma and mesothelioma, ERK5 is activated by PI3K/AKT signaling; in breast cancer, STAT3 enhances MEK5 expression; and in renal epithelial cells, TGFβ1-induced MEK5/ERK5 activation occurs through ALK and p38 MAPK, facilitating MEF2C-mediated transcription." (PMID 40672381, 2025). "STAT3 has many cofactors that are required for optimal STAT3 transcriptional activity and could be exploited for use in breast cancer therapies." (PMID 40507264, 2025). "Moreover, APE1 and STAT3 signatures are positively correlated in breast cancer data from TCGA and are positively correlated with proliferation and metastasis signatures." (PMID 41090323, 2025). "Given the distinct roles of STAT3 and STAT5 in normal mammary gland development and function, it would be interesting to further dive into the relationship between these two transcription factors and how STAT5 may modulate STAT3 pathogenesis in breast cancer." (PMID 40507264, 2025). "Likewise, although arising from distinct cellular contexts, aberrant FGFR1/STAT3 activation has been shown to trigger cell death in breast cancer cells." (PMID 41304754, 2025). "Additionally, apigenin re-sensitizes Adriamycin-resistant breast cancer (MCF-7/ADR) cells by inhibiting the signal transducer and activator of transcription 3 (STAT3) pathway." (PMID 40490812, 2025). "Thus, we have reason to believe that STAT3 plays a crucial role in BO’s therapeutic effect on breast cancer." (PMID 40076902, 2025).